CCNE1 (cyclin E1)
Diseases named in the same sentence as CCNE1 in open-access papers (continued):
Sharing a sentence is not in itself a finding about the gene and the disease.
cardiac hypertrophy (1 paper, 2015). "In this study, we have shown that down-regulation of miR-16 was accompanied by up-regulations of CCND1, CCND2 and CCNE1 in hypertrophic myocardium and cell models of cardiac hypertrophy." (PMID 25583328, 2015). "Therefore, this study demonstrates that increased expression of CCND1, CCND2 and CCNE1 were modulated at both transcriptional level and post-transcriptional level during cardiac hypertrophy." (PMID 25583328, 2015). "More specifically, several lines of evidence derived from our studies support that miR-16 inhibits cardiac hypertrophy through targeting CCND1, CCND2 and CCNE1." (PMID 25583328, 2015). "We have provided further evidence to support that miR-16 inhibited cardiac hypertrophy through targeting CCND1, CCND2, CCNE1 and cyclin/Rb pathway." (PMID 25583328, 2015). "Notably, our findings showing that down-regulation of miR-16 results in cardiac hypertrophy through up-regulating the expressions of CCND1, CCND2 and CCNE1 have raised many other questions." (PMID 25583328, 2015).
cardiac insufficiency (1 paper, 2022). "Studies have shown that 14-3-3 protein deficiency can affect the expression of cyclin E1 and p27Kip1, which are important genes in cell cycle regulation, leading to the arrest of cardiomyocyte development and the eventual occurrence of cardiac insufficiency." (PMID 35050860, 2022).
chronic hepatitis B (1 paper, 2019). "Therapeutic targeting of Cyclin E1 via RNAi has been shown to have robust anti-fibrotic activity in mice, and if this technology can be applied clinically in future, we predict that it will be most effective in those patients with chronic hepatitis B." (PMID 30923657, 2019).
chronic lymphocytic leukemia (1 paper, 2014). "Dinaciclib is currently being evaluated in a phase 3 clinical trial for chronic lymphocytic leukemia (CLL) and may have clinical potential in cyclin E1-dependent HGSOC as a chemosensitizing agent." (PMID 24624361, 2014).
chronic myeloid leukemia (1 paper, 2021). "Moreover, an ethanol extract of a traditional Chinese medicine, Eupolyphaga sinensis Walker induced G2/M arrest of a chronic myeloid leukemia cell line K562 accompanying through downregulation of cyclin D1, cyclin E1 and cdc25C." (PMID 34513690, 2021).
corticotroph adenoma (1 paper, 2024). "Martins and colleagues conducted a study to investigate the USP8 variant and its contribution to gene expression of cell cycle regulators including P27/CDKN1B, CCNE1, CCND1, CDK2, CDK4, and CDK6 in 32 corticotroph adenoma." (PMID 38862897, 2024).
endometrioid ovary tumor (1 paper, 2015). "In contrast, 43.8% of serous (21/48), 55.6% of mucinous (10/18) and 40.0% of endometrioid ovary tumor specimens (12/30) were strong for CCNE1 staining." (PMID 26204491, 2015).
fallopian tube carcinoma (1 paper, 2021). A carcinoma that arises from epithelial cells of the fallopian tube. "These seven cases of HGSC with confirmed CCNE1 amplification in the primary tumor had specimens from metastatic sites available for inclusion in this study and represented ovarian (n = 2), uterine (n = 2) and fallopian tube carcinomas (n = 3)." (PMID 34485660, 2021).
familial cancer (1 paper, 2021). "We examined the KConFab cohort, which is enriched for familial cancer mutations, for co-occurrence of germline BRCA1 mutation and high cyclin E1 expression." (PMID 34465787, 2021).
germ cell tumours (1 paper, 2023). "Intriguingly, transplantation of SSCs overexpressing both CCND2 and CCNE1 produced tubules consisting of spermatogonial clusters and an absence of haploid cells, resembling germ cell tumours and similar to TAT tubules." (PMID 37564373, 2023).
HIV-1 infection (1 paper, 2025). The type species of lentivirus and the etiologic agent of acquired immunodeficiency syndrome (AIDS). "The CCNE2, as the substrate of CDC4 was reported to act as a dependency factor to induce HIV Tat activity by encoding protein Cyclin E1, Cdk2 and Cyclin E. It is speculated that HIV-1 hijacks CDC4 to sequester it to prevent the degradation of CCNE2, facilitating HIV-1 infection in the target cells." (PMID 40260685, 2025).
kidney cancer (1 paper, 2019). Primary or metastatic malignant neoplasm involving the kidney. "In liver and kidney cancer, FAM83H expression was associated with the expression of cyclin D1, cyclin E1, and downstream signaling of the Wnt/β-catenin pathway." (PMID 31215499, 2019).
Lymphatic Metastasis (1 paper, 2025). Transfer of a neoplasm from its primary site to lymph nodes or to distant parts of the body by way of the lymphatic system. "However, no notable associations were found between CCNE1 expression and other clinicopathological characteristics, including age (P = 0.470), American Joint Committee on Cancer (AJCC) stage (P = 0.261), and lymphatic metastasis (P = 0.914)." (PMID 40346052, 2025).
metastatic melanoma (1 paper, 2011). A melanoma that has spread from its primary site to another anatomic site. "Although some of these genes (e.g. cell cycle genes CCND2, CCNE1 and PCNA) had fold changes that were in a different direction when compared to metastatic melanoma patients, this is likely to be due to the active growth of these cells in culture." (PMID 21615965, 2011).
neuroendocrine lung tumors (1 paper, 2021). "CCNE1 expression is upregulated and correlates with E2F1 status in high-grade neuroendocrine lung tumors." (PMID 33613291, 2021).
neuroendocrine tumor (1 paper, 2022). "Consistently with these literature reports, we found that IGF2BP1 affects expression of EZH2 and its downstream effectors regulating cell proliferation, such as CDK2 and CCNE1 in neuroendocrine tumor cells, thereby driving G1/S transition." (PMID 35565249, 2022).
oral cancer (1 paper, 2022). "We have also shown that ELDR induces G1/S phase by increasing cyclin E1 expression in oral cancer cells." (PMID 35378133, 2022). "The ELDR is highly expressed in oral cancer samples compared to normal cells and induces cell proliferation by increasing EGFR and ILF3/cyclin E1 signaling." (PMID 35378133, 2022).
ovarian serous cystadenocarcinoma (1 paper, 2024). A malignant serous cystic epithelial neoplasm arising from the ovary. "As cyclin E1 was independently associated with poor PFS, we proceeded to conduct bioinformatics analysis on the Ovarian Serous Cystadenocarcinoma TCGA cohort." (PMID 38612869, 2024).
Parkinson disease (1 paper, 2025). A progressive degenerative disorder of the central nervous system characterized by loss of dopamine producing neurons in the substantia nigra and the presence of Lewy bodies in the substantia nigra and locus coeruleus. "This study provides the first molecular insight into how CCNE1 exerts neuroprotective effects through the regulation of the ferroptosis key protein PARP16, offering a novel perspective for Parkinson's disease mechanism research." (PMID 41319014, 2025).
plasmacytoma (1 paper, 2023). Plasmacytoma is a localized mass of neoplastic monoclonal plasma cells that represents approximately 5% of all plasma cell neoplasms. "One study found that amplification of the cyclin E1 gene occurs in approximately 20% of high-grade plasmacytoma of the ovary and that Cyclin E1 induces entry into the S phase." (PMID 37446743, 2023).
prostate adenocarcinoma (1 paper, 2020). "SNHG12 and cyclin E1 (CCNE1) expression levels were also positively correlated in prostate adenocarcinoma (PRAD)." (PMID 33294456, 2020).
rectal cancer (1 paper, 2019). A primary or metastatic malignant neoplasm that affects the rectum. "The associations of PDE4 and Epac1 with AKAP95, Cx43, cyclin E1, and cyclin D1 in 44 rectal carcinoma samples were assessed." (PMID 30809467, 2019). "Meanwhile, correlations between PDE4 and Epac1, PDE4 and Cx43, PDE4 and cyclin E1, and Epac1 and Cx43 suggested synergistic effects of these proteins in promoting rectal carcinoma." (PMID 30809467, 2019). "In summary, there are some close correlations in PDE4, Epac1, cyclin E1, and Cx43 in rectal cancer." (PMID 30809467, 2019). "We previously assessed rectal carcinoma tissues and found higher positive rates of AKAP95, cyclin E1, and cyclin D1 compared with paracarcinoma tissues." (PMID 30809467, 2019).
retinoblastoma (1 paper, 2017). A malignant tumor that originates in the nuclear layer of the retina. "Isoflavones also inhibited human retinoblastoma growth in vivo; western blot analysis showed inhibition of mTOR and downregulation of cyclin E1 in an isoflavone-treated xenograft mouse model." (PMID 29179444, 2017). "This was supported by in vitro and in vivo data showing that isoflavones decreased mTOR phosphorylation, with a concomitant decrease in cyclin E1, which inhibited G1/S progression of human retinoblastoma Y79 cells." (PMID 29179444, 2017). "In the present study, inhibition of mTOR and downregulation of cyclin E1 occurred in isoflavone-treated human retinoblastoma Y79 cells and in an isoflavone-treated xenograft mouse model." (PMID 29179444, 2017). "Together, these results illustrate that isoflavones inhibit retinoblastoma tumour growth in vitro and vivo and that inactivation of the mTOR pathway and downregulation of cyclin E1 is involved in this action." (PMID 29179444, 2017). "In summary, the results of this study suggested that isoflavones reduced cell viability and triggered G1-phase blockage by down regulating cyclin E1 protein in human retinoblastoma Y79 cells in vitro and in vivo, mediated through the inhibition of the mTOR pathway." (PMID 29179444, 2017).
squamous cell carcinoma (1 paper, 2025). A carcinoma arising from squamous epithelial cells. "Our single-cell RNA-seq data demonstrated that CCNE1 expression was localized predominantly localized in epithelial cell subsets of both squamous cell carcinoma (SCC) and adenocarcinoma (ADC)." (PMID 41331376, 2025).
supraglottic cancers (1 paper, 2020). "Of note, cancer related proteins RB1, CHEK2, CCNE1, S6 and PIK3CA were higher in the supraglottic cancers, whereas PDL1 was higher in the glottic cancers." (PMID 33396315, 2020). "Cell cycle proteins including CHEK2, CCNE1, and phosphorylated RB1 were expressed at higher levels in the supraglottic cancers, which may indicate a disruption in the G1/S transition." (PMID 33396315, 2020).
Wilms tumor (1 paper, 2023). An embryonal neoplasm characterized by the presence of epithelial, mesenchymal, and blastema components. "Moreover, research has shown that MYLK-AS1 silencing can inhibit CCNE1 expression via the transcription factor TCF7L2, thereby regulating the cell cycle distribution and proliferation of nephroblastoma cells." (PMID 36964635, 2023).
tumor (407 papers, 2004 to 2026). "STICs have been found to share genomic characteristics with the subsequent tumor, including mutational profiles and amplification of the CCNE1 locus." (PMID 41279090, 2025). "Eight tumours carried focal amplifications and/or deletions involving known cancer genes, as well as potential chromosomal instability-associated genes, including CCNE1 amplifications and a rare amplification of BRCA1." (PMID 40952339, 2025). "To explore the association between CCNE1 and tumor prognosis, we performed further analysis via Kaplan-Meier plotters tool." (PMID 39591374, 2024). "We performed NGS including targeted and WES to identify the mutations and CN alterations (CNA) in each tumor sample, using a cutoff of CCNE1 CN≥6 to define CCNE1 amplification." (PMID 38717153, 2024). "The results indicate MET, ERBB2, SMAD4, and CCNE1 copy-number status is significantly associated with primary tumor site." (PMID 39062773, 2024). "Surprisingly, in another study, high CCNE1 expression (seen in 25% of tumours) was linked with better survival." (PMID 38612869, 2024). "Reportedly, the abnormal regulation of CCNE1 is effective in cell proliferation, which is associated with poor prognosis and disturbance of tumour immune microenvironment." (PMID 39648148, 2024). "We found that the expression of CCNE1 is related to clinical prognosis, immune infiltration of tumor cells, and gene mutation." (PMID 39591374, 2024). "This demonstrated that increased CCNE1 expression was associated with limited stromal and immune cell infiltration, leading to high tumor purity in ACC, TGCT, SARC, STAD, and SKCM." (PMID 36964635, 2023). "For example, alterations in the oncogenic driver genes FBXW7 (a negative regulator of cyclin E, encoded by CCNE1) and CCNE1 were observed in 6 patients across multiple tumour types (CRC, HGSOC, NSCLC)." (PMID 37120671, 2023). "We then explored the relationship between tumor antigens (CCNE1, PLK1, and SERPINA1) and ICD risk score using Pearson correlation analysis." (PMID 36393842, 2022). "Two tumor antigens, namely, CCNE1 and PLK1, were associated with poor prognosis and infiltration of antigen-presenting cells." (PMID 36393842, 2022). "Over-expression of CCNE1 has been found in many tumor types and can cause chromosome instability with enhanced proliferation." (PMID 33546249, 2021). "Several studies have reported that CCNE1 gene amplification or protein upregulation is associated with higher tumor grades and with a worse clinical outcome in a variety of cancers." (PMID 34070839, 2021). "Here, the authors profile AFPGC tumours using whole exome sequencing, and find amplifications in CCNE1 and ERBB2 that are associated with poor outcomes but are potential therapeutic targets, as shown in patient-derived xenografts." (PMID 34168152, 2021). "Concomitantly, Ccne1-depleted HCCs displayed less tumour-associated macrophages (TAM) positive for MHC-II (TAM1), which are considered as proinflammatory." (PMID 34830835, 2021). "As Cdk2-deficient tumours also displayed low expression of some DNA repair genes, we cannot exclude that distinct functions of CCNE1 for DDR require CDK2." (PMID 34830835, 2021). "Several studies have reported that CCNE1 gene amplification or protein upregulation is associated with higher tumour grades and a worse clinical outcome in a variety of cancers." (PMID 32295618, 2020). "The 2 RB1 mutated tumors had best overall response of PD, while the 1 tumor with CCNE1 amplification had SD." (PMID 33194700, 2020). "Of note, these results echo works in other malignancies where high cyclin E1 expression is associated with high-staging as well as tumor aggression and therapeutic-resistance." (PMID 33282745, 2020).
tumor (continued). "The results showed CCNE1 up-regulation mainly expressed in GC tissues and GC cell lines, also was associated with tumor node metastasis (TNM) stage and lymphatic invasion." (PMID 31072916, 2019). "A recent study indicated that homologous recombination deficiency and gain/amplification of CCNE1 copy number occur early in tumor progression and precede centrosome amplification in HGSOCs." (PMID 29560094, 2018). "Only one tumor with CCNE1 amplification also had a CDKN2A locus deletion associated with weak expression of CDKN2A (0.1%), as observed in HCC1806 cells." (PMID 28566333, 2017). "In the same context, miR-103 was found to be downregulated in tumor samples from spleen and liver of infected chickens, where it targets cyclin E1 and the transcription factor Dp-2, which normally causes suppression of cell migration and tumor formation." (PMID 27800484, 2016). "Cyclin E1 is a well established oncogene, and its overexpression, especially in a hyperstable form, leads to increased incidence of mouse neoplasia, and increased susceptibility to other oncogenes." (PMID 20180967, 2010). "Single-cell analyses revealed that CCNE1 expression was largely confined to epithelial cells and was associated with proliferative and structural remodeling pathways, with limited immune engagement across tumor types." (PMID 41331376, 2025). "We observed an association between CCNE1 expression and tumor pathological stages." (PMID 39591374, 2024). "Cyclin E1 and tumour stage were independently associated with PFS." (PMID 38612869, 2024). "Moreover, several databases including TCGA, GEPIA, HPA, TIMER and STRING databases were applied to explore the association of CCNE1 with prognosis, immune infiltration, and genetic mutation of tumor." (PMID 39591374, 2024). "Histological analysis of Ccne1-SIIN tumors showed an increased accumulation of transferred CXCR6-deficient OT-1 T cells in the tumor parenchyma relative to wildtype T cells, suggesting that releasing CD8+ T cells from CXCL16-CXCR6 mediated retention at the tumor margin can reverse T-cell exclusion." (PMID 38509063, 2024). "Elevated CCNE1 levels are often associated with increased tumor aggressiveness and invasiveness." (PMID 39591374, 2024). "CCNE1 is an established oncogene whose genomic amplification, overexpression and aberrant accumulation are associated with cell cycle misregulation, genome instability and tumour formation in mice." (PMID 39358461, 2024). "The insertion of HBV DNA into the CCNA2 and CCNE1 genes, which are associated with the G1/S transition of the cell cycle, disrupts the biological process and promotes tumor development; KMT2B is a tumor suppressor gene that prevents the uncontrolled growth and division of cells." (PMID 36992198, 2023). "In conclusion, this study provides important new insights into the biology of triple negative PABC and suggests that several copy number alterations, particularly 8p loss, TOP2A loss, ESR1 loss and CCNE1 gain are implicated in tumor progression during pregnancy." (PMID 35792986, 2022). "Additionally, the tumour microenvironment of Ccne1-deficient mice showed a reduction in immune mediators, myeloid cells and cancer-associated fibroblasts." (PMID 34830835, 2021). "Importantly, interventional deletion of Ccne1 was associated with reduced tumour burden at late stage, while inactivation of Cdk2 had absolutely no impact on HCC progression at all." (PMID 34830835, 2021). "In addition, sustained high-level expression of cyclin E1 can cause chromosome instability, which is conducive to tumor formation." (PMID 32123579, 2020). "Genetic analysis of tumor samples from the randomized clinical trial PALOMA-3 (fulvestrant treatment with palbociclib or placebo) showed that higher levels of the CCNE1 gene (encoding for cyclin E1) correlated with relative resistance to palbociclib." (PMID 30959874, 2019).